ERBB4 (erb-b2 receptor tyrosine kinase 4)
Diseases named in the same sentence as ERBB4 in open-access papers (continued):
Sharing a sentence is not in itself a finding about the gene and the disease.
breast carcinoma (continued). "To this end, we employed two HER2+ breast cancer cellular models (BT474 and SKBR3), which express intermediate/high and low ERBB4 levels, respectively." (PMID 35664762, 2022). "Patients with breast cancer showing low levels of FGFR2 and ERBB4 had worse OS relative to the other groups (p = 0.022)." (PMID 36601474, 2022). "For example, miR-323a-3p inhibits ErbB4 and affects depression, inhibits UHMK1 to down-regulate tumor growth in colorectal cancer, and inhibits PUM1/eIF2 axis in breast cancer." (PMID 35319011, 2022). "RFS analysis suggested that patients with breast cancer having low mRNA levels of FGFR2 had significantly worse RFS relative to the other groups (p = 0.04), whereas patients with high levels of ERBB4 had a better RFS than the opposite group (p = 9.5 × 10-5)." (PMID 36601474, 2022). "In conclusion, FGFR2, RET, ERBB4, MMP16, FN1, and SOX2 are potential targets of HON for overcoming TAM resistance in breast cancer." (PMID 36601474, 2022). "In summary, we have determined that ESR1 and ERBB4 are upstream and downstream genes, respectively, of DNAJC12 in breast carcinoma." (PMID 33718139, 2021). "In support of this study, one group also observed that WWP1 suppressed the expression of ErbB4/HER4 via ubiquitination and degradation in breast cancer." (PMID 34226507, 2021). "In breast carcinoma, ESR1 was positively correlated with DNAJC12 and ERBB4, and DNAJC12 was positively correlated with ERBB4." (PMID 33718139, 2021). "For example, in the UACC-893 breast cancer cell line, MOA target ERBB4 has a dependency score of only −0.18 and a corresponding CKI score of 3.65." (PMID 33205077, 2020). "Activation and overexpression of epidermal growth factor receptor (EGFR, also known as ErbB) family members, including EGFR (ErbB1 or HER1), HER3 (ErbB3), HER4 (ErbB4), and HER2 (ErbB2), govern multiple important cellular processes in breast cancer." (PMID 32223744, 2020). "Cell types that naturally produce ERBB4 ICD in their nuclei include mammary epithelial cells and other breast cancer cells." (PMID 30166589, 2019). "Other than miR-106-5p and miR-17-5p, miRNAs such as miR-375, miR-592, and miR-135a also influence breast cancer proliferation by modulating ESR1, ERBB4 pathway, and miR-135a function as prognostic marker in ER-positive breast cancer." (PMID 30989460, 2019). "It has been well elucidated that ErbB2 and ErbB4 activation initiates PI3K signaling cascades in different tissues such as skeletal muscle and breast cancer cells." (PMID 30971932, 2019). "Although most of these studies involved breast cancer with EGFR or ERBB2 overexpression, some researchers have conducted studies on the other HER family genes, including ERBB4." (PMID 26907936, 2016). "Several basal miRNAs (miR-125b, miR-142, miR-152, miR-146b, miR-222, and miR-212) have also been predicted to target luminal factors that have been previously identified in breast cancer, including ERBB2, ERBB3, ERBB4, and FOXA1." (PMID 27845906, 2016). "In vitro, the transforming growth factor-beta pathway has been shown to be upregulated by ErbB4 activation in T47D and MCF10A mammary carcinoma cells; in vivo, epithelial transforming growth factor-beta inhibits forward movement of TEBs." (PMID 25516216, 2014). "The CYT-1 isoform has antiproliferative activity in SUM102 mammary cancer cells, 32D bone marrow cells, and HC11 and MCF10A mammary epithelial cells, while CYT-1 ERBB4 promotes tumorigenesis in ovarian OVCAR-3 and SKOV-3 cancer cell lines." (PMID 25516216, 2014). "Nuclear ErbB-4 ICD has been shown to interact with Eto-2, a nuclear corepressor in breast cancer, and block Eto-2-dependent transcriptional repression." (PMID 22520625, 2012). "Although research into the role of ErbB receptor signalling in breast cancer has focused primarily on EGFR and ErbB2, it is becoming increasingly clear that both ErbB3 and ErbB4 also have important roles to play in this disease." (PMID 21396094, 2011).
breast carcinoma (continued). "For breast carcinomas, it was shown that neuregulin 1 (ligand for ERBB3 and ERBB4 tyrosine kinase receptors), but not Wnt3A, is indispensable for the isolation and long-term culture and expansion of breast cancer PDOs." (PMID 40863456, 2025). "Furthermore, efavirenz-inhibited LINE-1 action lowers the levels of recognized cancer genes in breast cancer, such as EGFR (epidermal growth factor receptor) and ERBB4 (erb-B2 receptor tyrosine kinase 4)." (PMID 39323697, 2024). "This suggests that miR-665 can be used as a negative prognostic biomarker for the survival time of breast cancer, eventually in combination with the rs1836724 SNP in ErbB4." (PMID 37894282, 2023). "In addition, ERBB4 has previously been reported to act as a mediator for acquired resistance against a different HER2-targeted drug, lapatinib, in breast cancer." (PMID 37072406, 2023). "To test this hypothesis, we first employed BT474 cells, a human breast cancer ERBB2-overexpressing cell line, which expresses ERBB4 at intermediate/high levels." (PMID 35664762, 2022). "We also analyzed the relationship between the mRNA levels of FGFR2, ERBB4, RET, FN1, MMP16, and SOX2 and tumor stages in breast cancer using GEPIA and found that the levels of FGFR2 were significantly upregulated in stage I and remained stable across stages II–X." (PMID 36601474, 2022). "Pathway analysis of the top 200 upregulated and 200 downregulated genes shows that systems known to be regulated by ErbB4 were altered in ErbB4−/− samples, such as RTK phosphorylation (cAMP, CREB, PKA, GPCRs); synaptogenesis and synaptic plasticity; and breast cancer and tumor microenvironment." (PMID 36241655, 2022). "Our data suggest that the activation of ERBB4 by NRG4 does not have a significant impact on HER2+ breast cancer cell proliferation." (PMID 35664762, 2022). "Collectively, our data suggest a potential tumor-suppressive role for ERBB4 in luminal A and HER2+ breast cancers, which could be manipulated to reduce tumor progression." (PMID 35664762, 2022). "A new problem was arisen whether there are genes in common that correlate with ESR1, DNAJC12, and ERBB4 expression in breast carcinoma, the cBioPortal tool was first used to output the lists containing genes related to ESR1, DNAJC12, or ERBB4." (PMID 33718139, 2021). "An unanswered question, though, is why this mechanism appears active in some ErbB4-expressing cells (e.g., macrophages, breast cancer) but not others (e.g., colonic epithelial cells)." (PMID 28230865, 2017). "In early-stage breast cancer, ERBB4 expression did not affect patient survival (5Y DRFS, low vs. high: 90.9 % vs. 90.2 %, p = 0.672)." (PMID 26907936, 2016). "However, due to either their irrelevance to human breast cancer, HER4/ErbB4, or breast cancer prognosis, 1380 studies were excluded." (PMID 27736797, 2016). "Finally, sustained expression of FL CYT-1 induced ERBB4-positive mammary tumor lesions in nearly all of the CYT-1 mice, indicating a tumorigenic function of this ERBB4 isoform in mammary epithelium." (PMID 25516216, 2014). "In contrast, Erbb4 ablation did not affect latency or histological grade of MMTV-Neu mouse mammary tumors." (PMID 23593223, 2013). "No similar difference was found in the accumulation of ErbB4 ectodomain in breast cancer cell culture medium (data not shown) when compared to the ectodomain levels in the extracellular space or serum of breast cancer patients." (PMID 22761786, 2012). "Using this cut-off, 50 (21%) out of the 238 breast cancer patients had an abnormally high ErbB4 ectodomain concentration in serum compared to none of 30 healthy controls (P = 0.002)." (PMID 22761786, 2012). "Significantly, the elevated serum ectodomain concentration did not correlate with the presence of nuclear ErbB4 immunoreactivity in matched breast cancer tissue samples." (PMID 22761786, 2012).
breast carcinoma (continued). "Unlike the other EGFRs, the oncogenic role of ErbB-4 in breast cancer is unclear since it appears to be correlated with prolonged patient survival and tumor growth suppression." (PMID 22520625, 2012). "Our observation of a positive correlation between ERBB4 mRNA levels and increased relapse-free patients’ survival in the luminal A subtype is in line with a previous study showing that the activation of ERBB4 signaling by NRG1 restrains the growth of breast cancer luminal cells." (PMID 35664762, 2022). "This signaling is ERBB2-specific and appears not to depend on ERBB2 heterodimers as in the context of the breast cancer cell line used here (expressing negligible ERBB4 levels), silencing of EGFR and ERBB3 does not impair the ERK-dependent AKT de-phosphorylation elicited by Abs." (PMID 33037285, 2020). "Interestingly, the study found that in the luminal breast cancer T47D cell line, CTGF and CYR61 were also upregulated by ERBB4 isoforms whereas SPARC was downregulated, suggesting a cell-type specific role for ERBB4 splice isoforms in regulating Hippo pathway target genes." (PMID 29534050, 2018). "The final member of the EGFR family, ErbB4, is not well characterized in cancer and while existing clinical data for the potential role of ErbB4 in breast cancer are contradicting a number of activating mutations were recently identifed in non-small cell lung cancer." (PMID 27597943, 2016). "SUM149 cells were isolated from an inflammatory breast cancer patient whose tumor was defined as “triple negative” but which nevertheless in our hands expressed detectable basal levels of ERBB1, ERBB2, ERBB3, and ERBB4 by immuno-fluorescence of cells fixed in situ." (PMID 27379204, 2016). "Potential oncogenic mutations in the protein tyrosine kinase domain and elsewhere in ERBB4 have been reported for melanoma, gastric carcinoma, colorectal carcinoma, nonsmall-cell lung carcinoma, and breast carcinoma, but most have not been functionally validated." (PMID 25516216, 2014). "Three categories had median P values below 0.001 (FDR = ~0): breast cancer estrogen signaling; MSigDB's set of ER-upregulated genes identified by Frasor and coworkers; and drug resistance and metabolism, which contains ESR1, BCL2, AR and ER's co-regulator ERBB4." (PMID 17845722, 2007). "Also, ERBB4 expression exhibited a log2 fold-decrease of 3.7 in the HER2-enriched group, therefore ERBB4 overexpression could have biological and prognostic significance for breast cancer." (PMID 35317849, 2022). "Similar to human ERBB2 driven breast cancer, tumors in ERBB2 transgenic animals show simultaneous increase in endogenous ERBB3 but not ERBB4 expression." (PMID 23593223, 2013).
schizophrenia (173 papers, 2007 to 2026). A major psychotic disorder characterized by abnormalities in the perception or expression of reality. "For ERBB4 rs839523, the C allele was associated with a higher odds of schizophrenia (OR = 6.724; 95 % CI: 0.743–60.862; p = 0.090), although this did not meet the significance level." (PMID 40977746, 2025). "The wild-type TT genotype of ERBB4 rs839523 showed a trend toward significance, suggesting a potential role in schizophrenia susceptibility." (PMID 40977746, 2025). "Loss-of-function mutations of both Erbb4 and nNos have been implicated in the pathophysiology of schizophrenia." (PMID 38396027, 2024). "ERBB4 is implicated in schizophrenia patients as one of the key dysregulated signaling in the development of cortical inhibitory GABAergic circuits indicated in GABA-enriched signature pairs." (PMID 38573526, 2024). "Many studies have indicated that the neuromodulin 1 (NRG1) and ErbB4 genes, the susceptibility genes of mental illness, are linked with the bipolar disorder and schizophrenia susceptibility genes." (PMID 38291418, 2024). "For instance, the schizophrenia susceptibility gene ErbB4 is exclusively expressed by GABAergic neurons in the cerebral cortex in mice." (PMID 37746155, 2023). "Recent studies demonstrate that deleting Erbb4, a schizophrenia-associated gene, in ChCs causes a schizophrenia-like phenotype in mice, indicating a causal relationship between ChC defects and schizophrenia." (PMID 37079499, 2023). "Conditional deletion of a schizophrenia susceptibility gene, the tyrosine kinase receptor Erbb4, from cortical and hippocampal inhibitory interneurons leads to synaptic defects, and behavioral and cognitive phenotypes relevant to psychosis in mice." (PMID 36573631, 2023). "Neuregulin-1 (NRG-1) gene and its receptor erb-b2 receptor tyrosine kinase 4 (erbB4) are significant risk factors for schizophrenia." (PMID 36620856, 2022). "Genes encoding the NRG1 protein and its receptor epidermal growth factor receptor 4 (ErbB4) are implicated in schizophrenia pathogenesis." (PMID 35682647, 2022). "Two ErbB4 alleles are significantly overexpressed in Ashkenazi schizophrenia patients, compared with matched controls." (PMID 36119496, 2022). "Neuregulin (NRG) is an NTF closely related to the development of the central nervous system and comprises NRG1-4 isoforms, among which NRG1 and its receptor ErbB4 are thought to be among the susceptibility genes for schizophrenia." (PMID 35337293, 2022). "This SNP is on the ERBB4 gene which is known to have a role in the pathophysiology of schizophrenia and bipolar depression and possible associations with childhood asthma." (PMID 35861116, 2022). "Cellular and behavioral phenotypes associated with miR138-5p inactivation are paralleled by an upregulation of the schizophrenia (SCZ)-associated Erbb4, which we validated as a direct miR138-5p target gene." (PMID 35290180, 2022). "Several studies have identified intronic variants of ErbB4 that are associated with schizophrenia, AD, and PD." (PMID 36119496, 2022). "The NRG1-ErbB4 pathway has been implicated in early schizophrenia association studies and rare structural variants in the ERBB4 gene have been identified in ASD, however, these results have not been replicated." (PMID 36224258, 2022). "The schizophrenia-associated susceptibility factors that interact closely with NMDARs like neuregulin 1 (NRG1) and its receptor ErbB4, both main genetic risk factors associated with schizophrenia." (PMID 34899420, 2021). "The neuregulin 1 (NRG1) ErbB4 module is at the core of an “at risk” signaling pathway in schizophrenia." (PMID 33871014, 2021). "Regarding TD, ERBB4 rs839523 CC genotype was associated with a high risk of developing TD and a higher chance for severe TD in a cohort of 153 European patients with schizophrenia." (PMID 35140610, 2021). "Neuregulin 1 (NRG1) and its receptor ErbB4 represent schizophrenia-associated susceptibility factors that closely interact with NMDAR." (PMID 34899420, 2021).
schizophrenia (continued). "Genetic variability of ERBB4 has been associated with cancer, schizophrenia, and amyotrophic lateral sclerosis." (PMID 35140610, 2021). "Genetic variations in neuregulin and its receptor kinase ErbB4, expressed exclusively by GABAergic neurons in the CNS, have been linked with schizophrenia." (PMID 34393751, 2021). "Neuregulins (NRGs) and their major neuronal receptor in the brain, ErbB4, have been genetically associated with schizophrenia." (PMID 32354758, 2020). "Natural genetic variants of Neuregulin1 (NRG1) and its cognate receptor ErbB4 are associated with a risk for schizophrenia." (PMID 32354758, 2020). "We had previously found that developmental perturbation of VIP interneurons by conditional deletion of the schizophrenia-associated gene ErbB4 caused a similar loss of state-dependent cortical regulation." (PMID 32343226, 2020). "Another recent study showed that deletion of the schizophrenia-associated gene, ErbB4, from TRN somatostatin (SOM) neurons impairs sensory selection in mice." (PMID 30837664, 2019). "Mutations of the ERBB4 gene differentially affected the treatment response to paliperidone in individuals with schizophrenia, implicating the neuregulin 1 (NRG1)–ErbB4 pathway for modulating the antipsychotic response." (PMID 30508120, 2019). "One putative risk gene is neuregulin 1 (NRG1), which signals via the receptor tyrosine kinase ErbB4, itself a schizophrenia risk gene." (PMID 29740596, 2018). "In the nervous system, NRG1 is thought to signal mainly through the ErbB4 receptor, and both NRG1 and ERBB4 have been genetically linked to schizophrenia." (PMID 29844389, 2018). "Both NRG1 and its receptor ErbB4 have been genetically linked to schizophrenia, and ErbB4 deficient mice display some schizophrenia-related phenotypes." (PMID 29844389, 2018). "NRG1 and the gene encoding its receptor, ERBB4, are risk genes for schizophrenia, although how alterations in these genes disrupt their function has not been fully established." (PMID 29844389, 2018). "Several previous studies found an increased expression of some splicing variants of ErbB4 in the dorsolateral prefrontal cortex of schizophrenia patients, as well as in peripheral lymphoblastoid cells." (PMID 28646138, 2017). "The genes encoding NRG1, ErbB3, and ErbB4 have been identified as susceptibility genes for schizophrenia, and a disruption in the ErbB4 gene has been described in schizophrenic patients." (PMID 26733804, 2015). "ErbB4 mutation uncovers flaws in brain development that are compatible with a neurodevelopmental model of schizophrenia, and it establishes a comprehensive model to study the basis of the disorder before symptoms are detected in the adult." (PMID 26733804, 2015). "In the present study, I focus on finding a cause-effect relationship between neurodevelopmental insults associated with genetic deletion of ErbB4 and the development of schizophrenia in the adult." (PMID 26733804, 2015). "The second group involves DISC1 and ERBB4; the latter being the gene with the highest ranking in terms of strength of association with schizophrenia GWAS data sets among the oligodendroglial and myelin related genes." (PMID 25506321, 2014). "The NRG1 growth factor and its receptor, ERBB4, have been shown to modulate neuronal functions and have been identified as leading schizophrenia risk genes." (PMID 25218581, 2014). "Schizophrenia-associated polymorphisms lead to increased expression of the CYT-1 isoform of ErbB4, which is coupled to PI3K signaling." (PMID 24592210, 2014). "Accordingly, impaired NRG1/ErbB4 signal is thought to underlie NMDA receptor dysfunction found in brain diseases such as schizophrenia." (PMID 23408472, 2013). "Many studies investigated the genetic association of NRG1 and ERBB4 with a risk of developing schizophrenia in various ethnic groups." (PMID 23301017, 2013).